BDNF (brain derived neurotrophic factor)
Diseases named in the same sentence as BDNF in open-access papers (continued):
Sharing a sentence is not in itself a finding about the gene and the disease.
COVID-19 (continued). "This leads us to infer BDNF to be a possible marker of adverse clinical outcomes for COVID-19 patients." (PMID 34957187, 2021). "A recent study reported that serum BDNF levels were lower in patients with severe or moderate COVID-19 disease than those with mild COVID-19." (PMID 33917718, 2021). "A recent study by Kirlangic and co-workers illustrated the results of a prospective study in which authors evaluated the fetal neurodevelopmental status through the quantification of circulating BDNF both in serum and umbilical cord from pregnant women hospitalized with COVID-19." (PMID 39596862, 2024). "They assumed that the etiology is a cross-reaction between the COVID-19 viral peak protein and antigens on the surface of the microtextured implants or related to excess production and secretion of brain-derived neurotrophic factor (BDNF) and nerve growth factor (NGF)." (PMID 39712691, 2024). "In summary, we found that BDNF (OR [95% CI] = 0.98 [0.96, 1.00], p = 3.53 ×10-2, proportion = 45.6%) and QPCT (OR [95% CI] = 0.99 [0.99, 1.00], p = 2.09 ×10-2, proportion = 16.8%) partially mediated the causal effect between LTL and COVID-19 susceptibility." (PMID 38882679, 2024). "Both BDNF and DCTN1 have been implicated in the neurological pathology associated with COVID-19." (PMID 38632526, 2024). "This decline in NGF and BDNF may lead to outcomes such as fatigue, memory impairments, and cognitive failure, outcomes now normally observed in some long-COVID-19 individuals or in the post-acute actions of SARS-CoV-2 exposure." (PMID 39596862, 2024). "Research indicates that blood concentrations of BDNF rise following infection with COVID-19 and could act as an early biomarker for forecasting the pathogenesis of COVID-19 in adolescents." (PMID 38882679, 2024). "However, another investigation revealed increased NGF and BDNF in saliva and serum during the acute COVID-19 phase, but reduced levels were observed 6 months after the acute phase." (PMID 36831321, 2023). "When analyzed with other organokines, the BDNF/adiponectin ratio predicted a significant risk for poor prognosis of COVID-19 in a cohort of 145 hospitalized COVID-19 patients (78 non-obese and 67 obese)." (PMID 37408184, 2023). "We predicted that BDNF and NFL presence in COVID-19 in aged individuals might be associated with severe morbidity and fatal outcomes." (PMID 36831321, 2023). "These risk factors are also associated with adipose tissue dysfunction and could have influenced the expression of BDNF, adiponectin, and leptin even before the onset of COVID-19 in the studied patients." (PMID 37408184, 2023). "Background and Methods: Severe COVID-19 is known to induce neurological damage (NeuroCOVID), mostly in aged individuals, by affecting brain-derived neurotrophic factor (BDNF), matrix metalloproteinases (MMP) 2 and 9 and the neurofilament light chain (NFL) pathways." (PMID 36831321, 2023). "Our study showed that levels of several autoantibodies to nervous system epitopes were associated with the clinical severity of COVID-19, including IgG antibodies to the dopamine 1 receptor, NMDA receptors, brain-derived neurotrophic factor (BNDF), and myelin oligodendrocyte glycoprotein." (PMID 36832180, 2023). "Furthermore, BDNF levels were even lower among those patients with COVID-19-related neurological manifestations and higher in those without neurological impairments but with high fever and dyspnea." (PMID 37408184, 2023). "Other data showed that the matrix metalloproteinase-9 (MMP-9)/BDNF ratio predicts more severe COVID-19 outcomes as MMPs may contribute to the tissue damage induced by COVID-19 as well as to the alteration of blood–brain barrier integrity." (PMID 36831321, 2023). "Interestingly, adult COVID-19 patients that required supplemental oxygen had even lower BDNF serum concentrations, showing an interplay between deregulated BDNF levels and viral hypoxia." (PMID 38002267, 2023).
COVID-19 (continued). "Apart from the role of inflammation on COVID-19 responses, brain-derived neurotrophic factor (BDNF) expression may have potential implications for severity of COVID-19 symptoms." (PMID 36189287, 2022). "the alteration of circulating or salivary NGF and BDNF levels in COVID-19 patients." (PMID 36579579, 2022). "We predicted that NGF and/or BDNF could be used as early biomarkers of COVID-19 morbidity in adolescents." (PMID 35626317, 2022). "Neuromodulator, neurotrophic, metabolic and systemic effects of BDNF could be suitable for predicting severe complications in COVID-19 patients 15,16." (PMID 36438922, 2022). "A decrease in BDNF level in COVID-19 patients depending on their condition has also been observed in other studies and it was negatively correlated with the severity of the patients’ condition, and its normalization followed the improvement of the clinical condition." (PMID 36294388, 2022). "Our study was devoted to the quantification of NGF and BDNF in COVID-19 patients, their transition from acute to remission phases, and the possibility to identify in this expression some predictors for the remission and course of COVID-19." (PMID 36579579, 2022). "Moreover, ebselen, a peroxynitrate scavenger, was found therapeutic in COVID-19, probably by restoring the physiologic BDNF/TrkB signaling, indicating a potential therapeutic value in PTSD." (PMID 34776871, 2021). "Understanding the relationship between the adipose tissue and its hormones, and their relationship with BDNF, may facilitate the development of new therapeutic and immunometabolic strategies for COVID-19 in obese patients." (PMID 34957187, 2021). "The confirmation of this theory may be reflected in one of the studies performed, in which patients suffering from COVID-19 were tested for serum BDNF levels." (PMID 34575258, 2021). "Indeed, serum BDNF levels were lower in patients with severe or moderate COVID-19 infection than those with mild COVID-19." (PMID 33917718, 2021). "Interestingly, serum BDNF levels didn't differ across severity groups in patients >60yrs, while a reduction of BDNF in patients <60 yrs was observed with the progression of COVID-19 severity." (PMID 34957187, 2021). "NGF and BDNF concentrations were comparable in the COVID-19 PCR and viral symptoms groups." (PMID 33917718, 2021). "BDNF was 35-fold higher in mothers with loss of smell and taste than mothers without loss of smell/taste in the COVID-19 group (p = 0.003)." (PMID 33917718, 2021). "We also predicted that the ratios of MMP-2/BDNF and MMP-9/BDNF could be considered early predictors of COVID-19 mortality, supposing the involvement of metalloproteinase and BDNF in the severe respiratory impairment associated with elevated mortality for COVID-19 infection." (PMID 39596862, 2024). "The association between COVID-19, neurotrophic factor reduction, and microglia activation emphasizes continuing research in exploring other therapeutic options aimed at moderating microglia overactivation, restoring NGF and BDNF presence, and decreasing inflammation." (PMID 39596862, 2024). "From a cellular standpoint, there is emerging evidence to suggest that COVID-19 may affect the brain via three main factors; 1) increased inflammatory response, 2) modulation of brain-derived neurotrophic factor (BDNF), and 3) disruption of glutaminergic pathways." (PMID 36189287, 2022). "Taken together, the mechanisms in which COVID-19 affects cognitive functioning appear to be multifaceted; underpinned by structural abnormalities, increased inflammatory responses, and impaired cellular pathways that support CNS homeostasis and functions (e.g., BDNF and glutamate)." (PMID 36189287, 2022). "Thus, it is possible that in presence of viral infection and metabolic disturbance, as in COVID-19, the relationship between BDNF and inflammation is modified or even, impaired (seen by high BDNF levels, ~100 ng/ml in obese patients with COVID-19 when they were admitted to hospital)." (PMID 34957187, 2021).
COVID-19 (continued). "However, NGF was elevated compared with BDNF in the exposed COVID-19 group." (PMID 33917718, 2021). "This study has shown that the blood levels of GH, FGF-1, BDNF, and PDGF are reduced after six months of COVID-19, and the reductions persist after fifteen months of recovery." (PMID 40709999, 2025). "This is the first study showing that the blood levels of GH, IGF-1, BDNF, and PDGF are reduced during acute severe COVID-19 and that the reduced levels persist for at least six months after recovery." (PMID 40709999, 2025). "Thus, BDNF may be involved in the regulation of ageing in COVID-19." (PMID 40709999, 2025). "The authors revealed that in COVID-19 patients, NGF milk concentration was lower than that of unaffected donors, while BDNF levels were unchanged between groups." (PMID 39596862, 2024). "The circulating levels of BDNF and NGF are reduced in adult COVID-19 patients compared to healthy individuals." (PMID 38002267, 2023). "Other investigations proposed that serum BDNF content and the BDNF/adiponectin ratio may serve as predictors of a worsened prognosis in COVID-19, especially for adult male patients, with BDNF also playing a subtle role in the neurological and mental outcomes of COVID-19." (PMID 36831321, 2023). "The results of this study can be useful in prospecting assumptions for the transition from acute to chronic COVID-19, at least for NGF and BDNF, and alternative candidates for the prognosis of therapy." (PMID 36579579, 2022). "The study investigated the relationships between clinical, biochemical parameters and active tissue mediators (MMP-9, MMP-8, BDNF, and VEGF A), that predominate during COVID-19, depending on the stage of the disease." (PMID 36438922, 2022). "Searching for a marker that would improve and simplify the ranking in COVID-19, the study intended to evaluate the relationship of MMP-9 with VEGF A, BDNF, and MMP-8 with the COVID-19 severity." (PMID 36438922, 2022). "On the other hand, our findings, by showing a high correlation between NGF and BDNF in both matrices, would suggest that at least one test and one parameter, the quick-and-easy one, depending on the situation, might be useful for the prediction and/or prognosis of COVID-19." (PMID 36579579, 2022). "Therefore, BDNF delivery systems may also help in prospective studies on recovery from long-term COVID-19 neurological complications and be considered as promising systems for personalized treatment of neuronal dysfunctions and prevention or retarding of neurodegenerative disorders." (PMID 35808102, 2022). "This study provides the first data on BDNF and NGF concentrations in human milk samples from mothers with a confirmed COVID-19 PCR test, mothers with previous viral symptoms suggestive of COVID-19, and unexposed mothers (control pre-pandemic 2018)." (PMID 33917718, 2021). "In summary, previous COVID-19 and mastitis infections changed differently the secretion of NGF and BDNF in human milk." (PMID 33917718, 2021). "Furin and plasmin are cell membrane serine proteases that under normal circumstances promote the maturation of BDNF, a neurotrophin involved in both PTSD and COVID-19." (PMID 34776871, 2021). "We found significant differences due to COVID-19 disease severity for both BDNF and NFL but not for NGF in the ratios with MMP-2 or MMP-9." (PMID 36831321, 2023). "We also confirmed and extended previous data, using ROC analyses, showing that the ratio MMPs (2 and 9) versus BDNF and NFL might be a useful tool to predict a fatal COVID-19 outcome." (PMID 36831321, 2023). "Furthermore, antibodies against NMDAR, brain-derived neurotrophic factor (BDNF), glutamic acid decarboxylase (GAD65), and the dopamine 1 (D1) receptor were increased in patients with severe COVID-19 and in those requiring oxygen." (PMID 37606433, 2023). "Using a surgical face mask in the group declaring mild symptoms of COVID-19 did not affect the post-exercise concentration of BDNF, adrenaline and testosterone." (PMID 37893874, 2023).
COVID-19 (continued). "We also confirmed and extended previous data showing that the ratios of MMPs (2 and 9) versus BDNF and NFL might be a useful tool to predict a fatal COVID-19 outcome." (PMID 36831321, 2023). "We also predicted that the ratios of BDNF and NFL with MMP-2 and MMP-9 could be considered early predictors of COVID-19 mortality." (PMID 36831321, 2023). "Testing the capability of this ratio to predict the COVID-19 stage by ROC curves, we found the MMP-9/BDNF could be a suitable marker for differentiating stages I/II (AUC 0.7597), stage I/III (AUC 0.9011), and stage I/IV (AUC 0.7727)." (PMID 36438922, 2022). "Among the defined COVID-19 groups, no changes in BDNF were observed not even in the critically ill group." (PMID 36438922, 2022). "Little is known about the changes in NGF and BDNF in adult COVID-19 patients, and no data are available when shifting from infection (acute) to non-infectious (chronic) SARS-CoV2 disease." (PMID 36579579, 2022). "The primary aim of this study was to investigate the possible associations between selected SNPs of OPRM1 (rs1799971), COMT (rs4680), BDNF (rs6265), and HTR1B (rs6296) and the presence of de novo long-term post-COVID pain in previously hospitalized COVID-19 survivors." (PMID 35893072, 2022). "Thus, the role of BDNF and IGF is found to be, and hence further studies are necessary to study the effect of these neurotrophic factors on neurogenesis in the post-acute COVID-19 phase." (PMID 36353605, 2022). "In COVID-19 there is mainly a decrease in BDNF level, and this may be due to the affinity of SARS-CoV-2 for the ACE2 receptor, which is involved in the BDNF formation pathway." (PMID 36294388, 2022). "BDNF did not correlate with NGF in the COVID-19 PCR group (p = 0.75) or in the viral symptoms group (p = 0.26)." (PMID 33917718, 2021). "Of particular interest, BDNF was 20.4-fold higher in mothers with headaches than mothers without headaches in the COVID-19 group (p = 0.048)." (PMID 33917718, 2021). "Antibodies against NMDA receptors (IgG), BDNF (IgG), GAD-65 (IgG), D1 receptor (IgG), and myelin oligodendrocyte glycoprotein (IgG) were elevated in patients with severe COVID-19 and those who required supplemental oxygen compared with those with mild COVID-19." (PMID 36832180, 2023). "However, among COVID-19 patients, BDNF serum levels were not statistically significant between patients with and without neurological manifestations derived from the infection." (PMID 37408184, 2023). "This exploratory study showed that four polymorphisms associated with pain experience (SNPs of OPRM1 (rs1799971), COMT (rs4680), BDNF (rs6265), and HTR1B (rs6296)), did not appear to predispose for developing post-COVID pain in previously hospitalized COVID-19 survivors." (PMID 35893072, 2022). "Searching for a marker that could improve and simplify the estimation of COVID-19 progress and considering the predictive potency of MMP-9, the study intended to evaluate the relationship of MMP-9 with VEGF A, BDNF, and MMP-8, concerning the development, severity of disease and outcomes of COVID-19." (PMID 36438922, 2022). "NGF and BDNF concentrations were not affected by the elapsed time from infection to milk collection in mothers with a confirmed COVID-19 PCR test or in mothers with viral symptoms suggestive of COVID-19." (PMID 33917718, 2021). "An exception was a negative correlation between MMP-9/BDNF with IL-10/IL-17 in moderately ill and a highly positive correlation of this ratio with MMP-8 in mild, moderate, and critically COVID-19 groups." (PMID 36438922, 2022). "The current study did not reveal significant differences in the presence of OPRM1 (rs1799971), COMT (rs4680), BDNF (rs6265), and HTR1B (rs6296) SNPs between previously hospitalized COVID-19 survivors with and without post-COVID pain." (PMID 35893072, 2022). "We observed that BDNF and NGF concentrations were comparable in COVID-19 PCR, viral symptoms suggestive of COVID-19, mastitis, and no mastitis groups." (PMID 33917718, 2021).
COVID-19 (continued). "We observed that NGF and BDNF concentrations varied between individual mothers in the three groups (COVID-19 PCR, viral symptoms, and unexposed) from non-detectable to 2140 pg/mL for NGF and from non-detectable to 207 ng/mL for BDNF." (PMID 33917718, 2021). "BDNF and NGF concentrations were not influenced by the elapsed time from infection to milk collection in mothers with a confirmed COVID-19 PCR and in mothers with viral symptoms suggestive of COVID-19." (PMID 33917718, 2021). "Regardless of the unchanged values of BDNF in different phases of COVID-19, we found a positive correlation between BDNF and MMP-9, MMP-8, and VEGF A, as well as a strong negative correlation of BDNF with IL-10 and cytokines ratios IL-10/IL-1, IL-10/IL-6, IL-10/IL-17, and IL-10/TNF-α." (PMID 36438922, 2022).